ERBB2 (erb-b2 receptor tyrosine kinase 2)
Diseases named in the same sentence as ERBB2 in open-access papers (continued):
Sharing a sentence is not in itself a finding about the gene and the disease.
tumor (continued). "TNBC is a heterogeneous group of tumours characterized by the absence of expression of histopathological markers such as the oestrogen receptor (ER), progesterone receptor (PgR) and ERBB2/HER2 oncogene." (PMID 29259228, 2017). "ErbB2-CAR- but not WT CIK cells proliferated, infiltrated and efficiently lysed tumor cell monolayers as well as 3D tumor spheroids." (PMID 29029499, 2017). "We show here that nectin-like molecule-4/cell adhesion molecule 4, known to serve as a tumour suppressor, interacts with ErbB3 in the absence of HRG and inhibits the HRG-induced dimerization of ErbB3 with ErbB2 and its activation." (PMID 28900130, 2017). "According to ASCO/CAP guidelines, ERBB2 amplification in just 20 adjacent BC cells suffices to establish a HER2-positive status, even if all other parts of the tumor are negative for HER2 protein expression and ERBB2 amplification." (PMID 27716627, 2016). "Concordance was 100 % for ERBB2, ESR1, PGR whereas for MKI67, one case containing 10 % tumor cells was negative in the non-macrodissected sample." (PMID 27389414, 2016). "Further immunohistochemistry showed the tumor was positive for cytokeratin 7 (CK7), CK20, villin, and ErbB2/HER2, but negative for gross cystic disease fluid protein-15 (GCDFP-15), ER, and PR." (PMID 25890325, 2015). "Although ErbB2/HER2 function can successfully be blocked with antibodies such as Herceptin/Trastuzumab, a subset of tumors is found to be non-responsive or tumor cells acquire resistance during therapy." (PMID 25630670, 2015). "Immunohistochemistry (IHC) showed that tumor cells were positive for epidermal growth factor receptor (EGFR) and ErbB2/HER2, but negative for estrogen receptor (ER) and progesterone receptor (PR)." (PMID 25890325, 2015). "HA binding to CD44 is involved in the stimulation of both receptor kinases (e.g., ErbB2, EGFR and TGFβ receptors) and non-receptor kinases (e.g., c-Src and ROK) required for a variety of tumor cell-specific functions leading to tumor progression." (PMID 24606718, 2014). "Comparing the ErbB2 positive with ErbB2 negative samples, PHLDA1 was found to be significantly less expressed in ErbB2 negative tumor slides (p<0.05)." (PMID 25238247, 2014). "Tumor immunophenotype was determined for ESR1 (44 positive, 16 negative), PGR (35 positive, 25 negative), and ERBB2 (19 scored as negative or 1+, 11 scored as 2+, 11 scored as 3+ and 19 were not assayed)." (PMID 23936250, 2013). "The risk allele of rs3803662 was highly correlated with a subgroup of basal tumours that expresses EGFR and CK5/6 but not ER, PgR and ERBB2." (PMID 23270421, 2012). "The rs3803662 genotype has been shown to associate most strongly with the ER/PgR positive and ERBB2 negative subgroups, which is the expression pattern of tumours of the luminal A subtype, further supporting that the effect seen in the BCAC study may be connected to luminal A tumours." (PMID 23270421, 2012). "Furthermore, the efficacy of EphA2 antibody-based therapy may depend on tumor type as no suppressive effect on tumor growth was observed in a colorectal tumor model, whereas mice harboring ErbB2 in mammary epithelium were sensitive to therapeutic inhibition of EphA2." (PMID 20224755, 2010). "Tumor length prior to IGF-IR downregulation did not significantly vary between the RM11A+Dox and RM11A+Dox/ErbB2 groups." (PMID 20825649, 2010). "Out of 13 samples with transcriptionally active NF-κB dimers, nine showed overexpression of EGFR and/or ErbB2 whereas out of 24 tumours without transcriptionally active NF-κB dimers only five showed overexpression of EGFR and/or ErbB2 (κ=0.476, P=0.004)." (PMID 17700572, 2007). "We identified 13 out of 17 IBC tumours with EGFR and/or ErbB2 overexpression compared to only one non-IBC tumour with EGFR and/or ErbB2 overexpression (κ=0.742, P<0.0001)." (PMID 17700572, 2007).
tumor (continued). "Using tumour phenotype (IBC or non-IBC), ER expression and presence of transcriptionally active NF-κB as independent variables and EGFR and/or ErbB2 overexpression as dependent variable, a logistic regression was performed." (PMID 17700572, 2007). "Using in vitro analyses of the tumor-derived cell lines, we have found no significant physical or functional interaction between EGFR (erbB1) and erbB2 in the presence of EGF (data not shown)." (PMID 16168116, 2005). "Thus, vaccinated mice were protected against challenge with Renca-lacZ/ErbB2, but not against ErbB2-negative Renca-lacZ cells still expressing bacterial β-galactosidase, which in naïve animals in our Balb/c-based model fails to serve as a tumour rejection antigen." (PMID 15812545, 2005). "Other studies that considered cell lines in culture have shown that indeed not all tumor cells respond to inhibition of ErbB receptors, despite exhibiting aberrant EGFR and/or ErbB2 expression." (PMID 15305194, 2004). "In primary tumours, no amplification was detected in early carcinomas, while amplification of ERBB and ERBB2 genes was detected in one (1.4%) and four (5.8%) out of 69 advanced carcinomas, respectively." (PMID 2386738, 1990). "Firstly, while ERBB2 and CLU expression were found to be elevated in tumor tissues compared to non-tumor tissues, their expressions were lower in the high-risk group compared to the low-risk group, indicating an inconsistency between prognostic trend and expression pattern." (PMID 39744560, 2025). "One possible mechanism is that in the presence of high ERBB2 levels, ERBB4 with bound NRG4 may form ERBB2:ERBB4 heterodimers, which possess oncogenic activity, rather than ERBB4:ERBB4 homodimers, which function as tumor suppressors." (PMID 37174100, 2023). "Hence, we aimed to retrospectively collect pathologically identified PPGL tumor tissues from our center and investigate the expression of apelin and SUCLG2 along with previously studied ERBB-2, CNTN4, CHGB, and SDHB in metastatic and non-metastatic PPGLs." (PMID 35574028, 2022). "Concurrent mutations in EGFR or ERBB2 and KRAS are not selected for and may be considered redundant in tumor cells, thus selective pressures may account for the mutual exclusivity of EGFR/ERBB2 and KRAS." (PMID 34204917, 2021). "Notably, canonical breast cell differentiation genes and molecular markers (KRT8, KRT18, KRT14, TP63, ERBB2, ESR1, PGR) were not differentially expressed, suggesting the cells maintain their differentiation state and tumor subtype." (PMID 34741115, 2021). "The mRNA expression levels of various RTK genes, including VEGFR-1, VEGFR-2, PDGFR-α, PDGFR-β, anaplastic lymphoma kinase (ALK), epidermal growth factor receptor (EGFR), ErbB2, and B-RAF were compared between the tumor and adjacent normal tissues collected from the patient." (PMID 33764261, 2021). "However, ERBB2-CAR CIK cell therapy was not as effective in the treatment of relapsed or progressive disease, even though the immune effector cells reached tumor sites and were increased in numbers compared with WT CIK cells." (PMID 33193388, 2020). "These tumours also on the protein level typically showed no or low expression of KRT5 and KRT14, aberrant expression of KRT20 and a low expression of EGFR, but a high expression of ERBB2." (PMID 30258198, 2018). "Thus, the impact of TCC on RNA relative quantification is gene-specific and as far as MammaTyper® genes ERBB2, ESR1, PGR and MKI67 are concerned the bias introduced by the inclusion of tissue surrounding the invasive tumor appears to be non-critical." (PMID 30342538, 2018). "While the parental HPDE cell line does not form tumours after orthotopic transplantation, expression of oncogenic KRASG12V and ERBB2 combined with short hairpin RNA-mediated knockdown of CDKN2A and SMAD4 produced lesions resembling invasive PDA after transplantation." (PMID 28272465, 2017).
tumor (continued). "When Necl-4 does not sufficiently inhibit the dimerization of ErbB3 with ErbB2, PTPN13 may complement the tumour suppressive function of Necl-4." (PMID 28900130, 2017). "No expression of CTNNB1, CTLA4, EPCAM, ERBB2, MET, p40, PD-L1 and SOX2 could be detected in any of the tumors, PD-L1 was negative in tumor as well as stromal cells." (PMID 26943575, 2016). "In tumor-bearing mice, the ErbB2-targeted bioluminescence imaging and therapeutic effect of EC1-GLuc-p53C were also observed specifically in BT474 tumors but not in MCF7 tumors, which does not overexpress ErbB2." (PMID 24069396, 2013). "Interestingly, two-thirds of the ERBB2 tumours were ER negative, yet they expressed significantly higher TOX3 mRNA than basal tumours (p = 0.02)." (PMID 23270421, 2012). "Two main groups were identified, one over-expressing markers typically found in sporadic luminal tumours such as GATA3, TFF1 and SCUBE2, and the other negative for ESR1, ERBB2 and the PR gene (PGR) (triple negative) and over-expressing genes from the basal layer such as CDH3, CRYAB and KRT5-17." (PMID 19826428, 2009). "Tumour phenotype was identified as the most predictive parameter to discriminate between tumour samples with EGFR and/or ErbB2 overexpression and without EGFR and ErbB2 overexpression (β=18.039; P=0.038)." (PMID 17700572, 2007). "The absence of chromosome 17 kataegis events co-localising with ERBB2 amplification in TCGA and ICGC PDAC tumours was further comparable with the molecular heterogeneity of PDAC and suggests this phenomenon may only present in a small sub-population of patients." (PMID 35392854, 2022). "Moreover, in HER2 positive BC, the response to HER2-targeted therapy could be modulated by the level of HER2 heterogeneity, defined as an area with ERBB2 amplification in >5% but <50% of tumor cells, or a HER2 negative area by FISH." (PMID 34573897, 2021). "For example, if genomic information from the primary tumour was used to inform therapeutic decision-making for patients 63 and 160, the AKT1 and ERBB2 amplifications would not have been evident and these patients would not have been considered for HER2 or AKT-mTOR pathway directed therapies." (PMID 25886454, 2015). "However, tumor cells may eventually develop resistance to the anti-erbB3 Abs, since the Abs like EGFR/erbB2-targeted therapies just inhibit signaling without altering expression of the erbB receptors." (PMID 24886126, 2014). "Furthermore, this study underscores the importance of identifying patients who may benefit from novel HER2-targeted therapies, such as T-DXd, by implementing comprehensive and routine ERBB2/HER2 testing, even in tumor types where such approval is not standard practice." (PMID 40828885, 2025). "We did not observe a correlation between the expression of SRC-3, ErbB-2, hTERT, PTEN, FoxO1, Bcl-2, SMAD4, c-myc, Hsp70, Hsp90 and CHIP expression in BxPC-3 cells, this result could be explained by feedback of complicated signaling network in different tumor environments." (PMID 24722501, 2014).
cancer (10,081 papers, 1990 to 2026). A tumor composed of atypical neoplastic, often pleomorphic cells that invade other tissues. "The model effectively captured cancer-associated genes and pathways—particularly those related to ERBB2 and PI3K/AKT signaling, immune regulation, and cell cycle control—showing superior biological relevance and interpretability compared to baseline methods." (PMID 41761059, 2026). "Rare ERBB2 activating alteration classes included TMD mutations (0.08% prevalence across select cancers) and Ex16Alt (0.04% prevalence) either through intragenic deletion (Ex16Del) or splice-site mutations (Ex16Splice)." (PMID 40178042, 2025). "HER2 is encoded by the oncogene ERBB2, and studies have shown that the activation of HER2 mutations is an important pro-cancer factor." (PMID 40296904, 2025). "The landscape of ERBB2 mutations varied substantially across cancer types at both the domain and codon levels." (PMID 40178042, 2025). "ERBB2 (HER2) aberrations, including amplification, overexpression, and activating mutations, are well-established crucial oncogenic drivers in various cancer types." (PMID 40828885, 2025). "Afatinib, for example, is linked to ERBB2 (HER2), a receptor tyrosine kinase overexpressed in numerous cancers." (PMID 41304759, 2025). "Sensitivity for detecting ERBB2 amplification was lower than for detecting ERBB2 mutations across all cancers analyzed (33.3% vs. 72.3%, N = 1,922)." (PMID 40178042, 2025). "It is a transmembrane growth factor receptor with intrinsic tyrosine kinase activity, encoded by the ERBB2 gene on chromosome 17q12, and is critical for cancer cell growth and survival." (PMID 40620714, 2025). "ERBB3 alterations were found to co-occur with ERBB2 mutations in all cancer types assessed except for NSCLC." (PMID 40178042, 2025). "Several factors are thought to influence the efficacy of HER2-targeted treatment directed at patients with ERBB2-mutated cancer, including cancer type, domain of the ERBB2 oncogenic variant, as well as concurring co-mutations and other genomic alterations." (PMID 40770324, 2025). "Although there were shared ERBB2 mutational hotspots across cancers (e.g., S310), certain mutation sites were uniquely enriched in specific contexts." (PMID 40178042, 2025). "Results showed a high risk of cancer recurrence (relapse risk score 59), with a low probability of pCR (pCR likelihood score 11) and low ERBB2 expression (ERBB2 mRNA level score 20), consistently with the previous IHC/FISH borderline result." (PMID 40199689, 2025). "NSCLC harbored a markedly high incidence of TMD mutations (6.0% of ERBB2 mutations compared with 1.0%–2.1% in other cancers)." (PMID 40178042, 2025). "This study investigates the treatment efficacy and mutational landscape of patients with ERBB2-mutated cancers receiving HER2-targeted therapy." (PMID 40770324, 2025). "Hallmark Apoptosis (Overlap Genes: CCNA1, NEFH, ERBB2): Apoptosis or programmed cell death is critical in cancer progression." (PMID 39000413, 2024). "Overexpression of ERBB2 in cancer cells has been linked to metastasis, poor response to cancer treatment, and poor prognosis." (PMID 38696425, 2024). "“Amplifications” of ERBB2 are the main type of genetic alteration in most cancers followed by “Mutations” and then “Multiple Alterations”." (PMID 39409883, 2024). "Erb‐b2 receptor tyrosine kinase 2 (ERBB2)‐activating mutations are therapeutically actionable alterations found in various cancers, including metastatic breast cancer (MBC)." (PMID 38287892, 2024). "For instance, an examination of 178 cancer-related genes in a cohort of 110 patients with MIBC revealed that ERBB2 missense mutations are only observed in patients who respond positively to NAC." (PMID 38398192, 2024). "The advent of such ADCs has been revolutionizing the field, particularly by expanding the potential applications beyond traditional HER2-positive cancers to include tumors with lower expression levels of HER2 or with ERBB2 mutations." (PMID 38398191, 2024).
cancer (continued). "To employ this mechanism for cancer immunotherapy, we generated NKG2D-engaging bispecific antibodies that selectively redirect immune effector cells to cancer cells expressing the tumor-associated antigen ErbB2 (HER2)." (PMID 39267747, 2024). "Overexpression or abnormal expression of these receptors can lead to cancer progression, with ErbB2 (HER2/neu) being notably implicated in many cancers." (PMID 39199633, 2024). "In a group of 587 studied patients with epithelial ovarian cancer, SNPs at PIK3CA rs9838117 and ERBB2 rs1058808 loci associated with cancer cell signaling were found to be correlated with the risk of cancer." (PMID 38275400, 2024). "Meanwhile, NCCN_cancer targets were mainly composed of ERBB2 amplification (40%), BRCA2 pathogenic mutations (40%), and CDKN2A oncogenic mutations (20%)." (PMID 38661052, 2024). "Too many copies of the ERBB2 gene encoding the HER2 protein result in its overexpression in cancer cells." (PMID 38338997, 2024). "For example, the ligand EGF in cancer epithelial cells is significantly associated with the receptors ERBB2 (P value = 0.009) and EGFR (P value = 0) in CAFs, suggesting a potential signaling cascade from the former to the latter." (PMID 38279156, 2024). "ERBB2 point mutations have been reported in canine pulmonary carcinomas (38% cases), with the majority (93%) being hotspot ERBB2 p.V659E mutations, comparable to activating mutations at the same site in human cancer." (PMID 38787171, 2024). "ERBB2 is a member of the epidermal growth factor receptor family and functions upstream of signaling pathways frequently implicated in cancer, such as the MAPK or the mechanistic target of rapamycin (mTOR) signaling pathways." (PMID 38778091, 2024). "Further, the authors report that HER2 (ERBB2) gene amplification was observed in 5 (12%) of 42 carcinomas with pathogenic SMARCA4 mutation." (PMID 38656564, 2024). "These mice are transgenic for a mutated version of the rat ErbB2/neu receptor gene and develop multifocal carcinomas in all mammary glands with 100% penetrance." (PMID 38892447, 2024). "ERBB2 is overexpressed in some cancers, and its overexpression is associated with aggressive behavior and poor prognosis." (PMID 37174100, 2023). "The engineered destabilized ARE 3’UTR of ERBB2 is agnostic to these mutations and reliably controlled and degraded the ERBB2 transcript in this cancer." (PMID 37359373, 2023). "It is surprising to find that in these results, the engineered constructs destabilized ERBB2 and led to a significant loss of aneuploidy in the cancers carrying the constructs compared to the controls." (PMID 37359373, 2023). "Clustering of the enriched motifs revealed the close concordance of AP-1 motif association with more accessible regions in ERBB2-positive OAC cancer samples and regions that closed in OE19 cells after ERBB2 inhibition." (PMID 36694726, 2023). "Too many copies encoding the ERBB2 gene of the HER2 protein affect its overexpression in the cancer cell." (PMID 36902163, 2023). "Within 8 days, all the cancer cells transfected with ERBB2 3’UTR-destabilizing elements showed loss of viability and increased caspase 3/7 expression compared to the wildtype cells and the vector control cells." (PMID 37359373, 2023). "Many of the identified genes are present in the COSMIC Cancer Gene Census53 of genes causally implicated in cancer, including ERBB2, which had the highest inferred K* of any statistically significant COSMIC genes in two biopsies." (PMID 38092737, 2023). "Erbb2-driven carcinomas with Cse1l deficiency outgrow less irregularly from mammary ducts, and NLS-attenuating mutants or variants of HER2 favor escape in 3D culture." (PMID 37055441, 2023).